CD36 (CD36 molecule (CD36 blood group))
Diseases named in the same sentence as CD36 in open-access papers (continued):
Sharing a sentence is not in itself a finding about the gene and the disease.
tumor (continued). "The mean percentages of tumor M-LECPs co-expressing SIRP-a, CD36, and DAP12 were 35.26 ± 4.13, 58.81 ± 12.33, and 93.36 ± 1.99, respectively." (PMID 40507286, 2025). "PLIN2 facilitates macrophage polarization toward the M2 phenotype and activates the CD36-dependent EMT pathway in CRC cells, thereby enhancing tumor aggressiveness." (PMID 40640171, 2025). "Preclinical studies have shown that blocking CD36, especially in combination with FASN inhibitors and anti-PD-1 therapy, produces synergistic anti-tumor effects, suggesting a promising combinatorial treatment strategy." (PMID 41476608, 2025). "Specifically, CD36, FABP4, PLIN1, SCD5 and ACSL4 were significantly downregulated in tumor samples (p < 0.05)." (PMID 40860798, 2025). "Furthermore, PI3K/AKT signaling directly regulated glucose transporter 4 and glucose metabolic enzymes, therefore, combined PI3K and CD36 inhibitors might restrict the energy supply for tumor growth by synergistically reducing exogenous FAs and glucose resources." (PMID 39920872, 2025). "Specifically, we observed a significant down-regulation of some of the most relevant genes in the PPAR pathway (CD36, FABP4, PLIN1, PLIN4, SCD5 and ACSL4) in tumor tissue samples." (PMID 40860798, 2025). "Conversely, CD36-mediated ferroptosis has been shown to impede CD8(+) T cell effector function, thereby attenuating their anti-tumor capacity." (PMID 40260246, 2025). "By facilitating uptake of long-chain fatty acids and oxidized lipoproteins, CD36 enhances PPAR-β signaling, mitochondrial fitness, and NAD+/NADH balance, thereby promoting Tregs survival in nutrient-poor tumor microenvironments." (PMID 41459507, 2025). "Treatment with the CD36 inhibitor sulfosuccinimidyl oleate (SSO) slightly reduced tumor cell proliferation when used at higher concentrations, indicating that tumor cells from PyMT-RIDad mice appeared to rely on CD36 expression on their surface." (PMID 40526430, 2025). "On The other hand, we identified a complex interplay involving CD36, CXCL11, GZMB, MT2 A, and CD8 + T cells that regulates immune function and tumor cell cycle processes." (PMID 40382758, 2025). "The uptake of free fatty acids by BC cells is facilitated by various proteins, such as CD36, FABPs, and carnitine palmitoyltransferase 1 (CPT1), which have implications for tumor progression and invasiveness." (PMID 40548063, 2025). "In tumor cells, CD8 T cells take up oxidized lipids through CD36, thereby inducing lipid peroxidation." (PMID 41236698, 2025). "Fatty acid (FA) metabolism in GC is heavily reliant on key mediators such as fatty acid translocase CD36 and carnitine palmitoyltransferase, which play pivotal roles in tumor progression and immune modulation within the TME." (PMID 40028336, 2025). "Macrophages in dead tissue areas, which are rich in lipids and highly express CD36 and FABP5, transfer fatty acids to nearby tumor cells." (PMID 40904700, 2025). "The expression levels of the genes CD36, CXCL14, DAB2, MARCKS, ENPEP, and TIMP1 in normal, tumor, and metastatic tissues were analyzed using various statistical methods." (PMID 40565366, 2025). "Functionally, siRNA-mediated knockdown of CD36 markedly suppressed the proliferation of DLBCL cells, underscoring its crucial role in promoting tumor growth." (PMID 41041664, 2025). "In tumor-infiltrating CD8+ T cells, CD36 can provoke lipid peroxidation and ferroptosis, impairing cytokine production and cytotoxic function." (PMID 41550652, 2025). "We observed that the tumor weight in the PLIN2 overexpression group was greater than that in the control group, which was reversed by the CD36 inhibitor." (PMID 40640171, 2025).
tumor (continued). "Moreover, CD36 has been associated with metastatic processes in various cancers, including GC, where it might enhance the metastatic potential of cancer cells by promoting epithelial-mesenchymal transition (EMT) and tumor invasiveness." (PMID 40061897, 2025). "Tumors actively stimulate adipocyte lipolysis via the adipose triglyceride lipase (ATGL)-dependent pathway, leading to FFA release, which is transferred to cancer cells via CD36 or FATPs to fuel fatty acid oxidation (FAO), enhancing tumor aggressiveness." (PMID 40616161, 2025). "To assess the nature of intercellular interactions in SARIFA areas, we analyzed the expression of CD36 and FABP4, genes known to be involved in alterations of fatty acid metabolism at the interface between tumor cells and adipocytes." (PMID 41228384, 2025). "The studies demonstrate the impact of CD36 on the prognosis of AML across different categories, such as survival, remission, chemotherapy resistance, and tumor cell proliferation." (PMID 40527069, 2025). "Inhibition of ferroptosis can bolster the anti-tumor activities of CD8 + T cells, and the expression of CD36 correlates with poorer patient prognoses." (PMID 40285867, 2025). "Consequently, CD36-mediated lipid-driven immunosuppression and tumor proliferation contribute to poor prognosis in certain cancers, whereas its association with immune-inflamed or metabolically distinct microenvironments may underlie protective effects in others." (PMID 41550652, 2025). "CD36-mediated FA uptake can induce LPO and ferroptosis in tumor-infiltrating CD8+ T cells, blocking CD36 and restoring their antitumor activity." (PMID 40134420, 2025). "These tumors often exhibit elevated expression of lipid-related enzymes (e.g., FASN, ACC), transporters (CD36), and regulators (SREBP1), all of which support tumor growth, metastasis, and immune evasion." (PMID 40487761, 2025). "Tumor-recruited M-LECPs retained this profile in vivo as shown by expression of prominent fusogenic markers SIRP-a, CD36, and DAP12 in 60–90% of LYVE-1+ cells in mouse and human BC." (PMID 40507286, 2025). "For instance, adipocytes serve as a lipid source, enhancing the expression of CD36, CPT1A/B, FATPs, and FABPs in tumor cells, thereby promoting FAO, which in turn supports tumor cell proliferation and invasive capabilities." (PMID 40616161, 2025). "Specifically, CD36-dependent promotion of P38 phosphorylation leads to lipid peroxidation and ferroptosis, impairing the cytotoxic function of CD8+ tumor-infiltrating lymphocytes (TILs) and effectively suppressing the antitumor immune response." (PMID 40028336, 2025). "Notably, CD36 protein levels were downregulated after SDHB was overexpressed in both cell lines, which is in line with the finding that CD36 protein levels were higher in tumor samples from patients with SDH-deficient GISTs than in those from patients with SDH-competent GISTs." (PMID 41184234, 2025). "Accordingly, we observed that CD36 expression was strikingly high in HER2 + BC cases characterized by high expression of the basal marker CD44v6, revealing enrichment of CD36 in tumor cells characterized by a mesenchymal/basal-like phenotype." (PMID 39833955, 2025). "Targeting Treg metabolism, for example, through inhibition of CD36 or MCT1, is therefore being explored as a strategy to selectively impair tumor-infiltrating Tregs while sparing systemic tolerance." (PMID 41459507, 2025). "CD36 in the heart and FATPs or FABPs in the liver suggest higher expression levels than CD36 and FATP expressed on the cell membrane of the tumor due to the substantial impact of transporters in the early post-administration period." (PMID 39062992, 2024). "Studies show that CD36 inhibition diminishes cancer cell proliferation via modulating CD8+ T-cell and Treg-cell activities to increase anti-tumor immunity." (PMID 39062552, 2024). "Stratified survival curves based on the expression of CD36 and MYD88 were plotted for these tumours." (PMID 38742843, 2024).
tumor (continued). "In conclusion, through wet experiments validation, we demonstrate that CD36 and MYD88 promote tumour proliferation, invasion, and migration in OS." (PMID 38742843, 2024). "The genetic depletion of CD36 limits oxidative metabolism and the induction of the immunosuppressive mechanisms, resulting in a CD8+ T cell-dependent delay in tumor development." (PMID 38370376, 2024). "Specifically, we found that CD36 and CD47 were ubiquitously expressed in tumor cells across virtually all types of cancers evaluated in this study." (PMID 39627379, 2024). "Given the ample evidence for the major role of lipid metabolism in tumor progression in cancer in general, but also in the context of PCa, we studied the immunohistochemical protein expression of FABP4 and CD36, both key players in fatty-acid metabolism." (PMID 38216952, 2024). "In contrast, overexpression of GPX4 or depletion of CD36 can save the effective death of cytotoxic CD8+ T cells and enhance their anti-tumor ability." (PMID 39359721, 2024). "Mechanistically, increased CD36 expression in human and murine CD8+ tumor-infiltrating lymphocytes correlated with decreased cytokine production and impaired antitumor activity." (PMID 39742252, 2024). "Similarly to the presence of TAF and SARIFA-positivity, upregulation of CD36 and FABP4 is associated with worse outcomes in univariate Kaplan-Meier analysis in TCGA-CRC regarding most endpoints, strengthening the association between an increased lipid metabolism and an aggressive tumor behavior." (PMID 39147895, 2024). "Among that, the protein expression of IGF2BP3, B2M, CD36, CDKN1A, ANKRD33B, and LHFPL2 were up-regulated; However, the protein expression of APP and CTDSPL was low in both normal and tumor tissues." (PMID 39470474, 2024). "Cystine consumption by tumor cells disrupts cystine/glutamate exchange in CD8+ T cells, which thus triggers CD36-mediated lipid accumulation and aberrant ROS production, leading to T-cell exhaustion and ferroptosis." (PMID 38360744, 2024). "Increased expression of FA transporters, such as CD36, FABPs, and Solute Carrier Family 27 (SLC27), in the plasma membrane enhances lipid uptake by tumor cells." (PMID 39227970, 2024). "We also developed a scoring system to distinguish different levels of CD36 and CD47 expression in tumor cells, based on the data from the escalation phase." (PMID 39627379, 2024). "Expression of ANGPTL4, CD36 and FABP4, proteins involved in fatty acid metabolism, was analyzed in marginal tumor cells using an immune reactive score." (PMID 39456610, 2024). "To investigate if CD36 and CD47 can be more widely used as biomarkers for other cancer types, we measured CD36 and CD47 expression in tumor microarrays (TMA) from multiple tumor types." (PMID 39627379, 2024). "CD36 plays a crucial role in regulating lipid balance by preferentially absorbing MUFA during extracellular matrix detachment and tumour advancement." (PMID 39083563, 2024). "In tumor-infiltrating CD8+ T cells, excess fatty acid uptake is mediated by CD36, leading to reduced cytotoxic cytokine production and impaired antitumor ability." (PMID 38319449, 2024). "CD36 facilitates the uptake of fatty acids by CD8+ T cells in the TME, inducing lipid peroxidation and ferroptosis, thus impairing the anti-tumor capabilities of CD8+ T cells." (PMID 39614322, 2024). "Humanised CD36 antibodies, exemplified by clones 1G04 and Ona-0-v1, mirror the efficacy of JC63.1 and diminish tumour initiation and metastasis, particularly in liver and lung cancer models, by modulating lipid uptake." (PMID 38610991, 2024). "In the tumor microenvironment, where macrophages and CD8+ T cells take up lipids via CD36, the knockout of CD36 in CD8+ T cells in mice diminishes lipid peroxidation and inhibits ferroptosis." (PMID 39857243, 2024). "We found that the patient response rate was strongly correlated with the level of CD36 and CD47 expression on the surface of tumor cells." (PMID 39627379, 2024).
tumor (continued). "The tumor cells in SARIFAs express FABP4 (Fatty Acid Binding Protein 4) and show a higher expression of CD36, which indicate the capability of the tumor cells for taking up and breaking down fatty acids." (PMID 39335115, 2024). "Our examination of CD36 and MYD88 as therapeutic targets reveals a compelling avenue for personalised tumour therapy." (PMID 38742843, 2024). "The stimulation of TSP-1 simultaneously targets both CD36 and CD47 harnessing the full anti-tumor activity of TSP-1." (PMID 38218979, 2024). "Abundant FFAs produced by tumor cells can provide a metabolic advantage for Treg cells survival while blocking FFA uptake of Treg cells by ablating CD36, a scavenger molecule on the cell membrane, can attenuate their suppressive functions." (PMID 39164472, 2024). "While FABP4 expression was comparable between the groups, we observed higher expression levels of CD36 and ANGPTL4 in tumor cells at the invasive front in overweight/obese TNBC patients." (PMID 39456610, 2024). "TSP-1 reprograms the TME via binding to CD36 and CD47 to induce tumor and endothelial cell apoptosis as well as immune modulation in the TME." (PMID 38218979, 2024). "To investigate alterations in tumour metabolism and microenvironment, we performed immunohistochemical staining for FABP4, CD36 and CD68." (PMID 38926671, 2024). "Recently, it was reported that the influx of extracellular fatty acids through CD36 into CD8+ T cells, the main players in anti-tumor immunity, induces ferroptosis and reduces anti-tumor immune functions." (PMID 38719806, 2024). "The CD36/TLR2/TLR6 form a coreceptors complex on DC surface, and the exogenous ligands of tumor‐derived oxLDL and HMGB1‐gDNA complex join the coreceptors complex through binding CD36 and TLR2/TLR6, respectively." (PMID 37786300, 2023). "We found that the Arf1‐ablated tumor cells release oxLDL, HMGB1‐gDNA complex, and also induce expression of CD36, TLR2, and TLR6 in DCs." (PMID 37786300, 2023). "We examined the number of CD36+CD8+ T cells in tumors, non-tumor tissues and PBMCs taken from 11 NSCLC patients." (PMID 37085798, 2023). "Finally, interrogation of TCGA data sets revealed that the expression of the peroxisome marker ABCD3 and UGCG was also positively correlated with CD36 expression in other tumor types, suggesting that combined inhibition of peroxisomes and UGCG may have broader clinical utility." (PMID 37616051, 2023). "CD36 in TAMs mainly mediates extracellular lipid uptake, especially ox-LDL, and the internalization of tumor cell-released lipids in EVs." (PMID 37700339, 2023). "They find that the Arf1‐ablated tumor cells release OxLDL, HMGB1, and genomic DNA, which together bound to a coreceptor complex of CD36/TLR2/TLR6 on DC surface." (PMID 37786300, 2023). "Secondly, cancer cells respond to hypoxia by upregulating the expression of fatty acid translocase (CD36), facilitating increased uptake of FFAs by the tumor cells." (PMID 37841917, 2023). "Several preclinical studies have demonstrated the efficacy of targeting fatty acid transporters such as fatty acid translocase, CD36, and fatty acid binding protein 4 (FABP4) in reducing tumor growth in various cancer types." (PMID 37233659, 2023). "CD36+CAF-derived MIF potentiated the capacity of MDSCs to promote immunosuppressive TME and tumor stemness via IL-6/STAT3 activation." (PMID 38065972, 2023). "This explains why the gradual upregulation of CD36 expression reduces the infiltration of intra-tumoral CD8+ T cells through ferroptosis during tumor progression, leading to a gradual decline in anti-tumor immune function." (PMID 38288118, 2023). "This first-in-class compound is a cyclic pentapeptide that has been demonstrated to reprogram myeloid-derived suppressor cells (MDSCs) to produce TSP-1 in the TME, which can then bind to CD36 and CD47 on tumor and endothelial cells." (PMID 37371076, 2023).
tumor (continued). "In summary, these results indicate that miR-3180 suppresses tumor growth and metastasis in vivo via SCD1 and CD36." (PMID 37041584, 2023). "In this study, we discovered the suppressive function of CD36+CD8+ T cells in NSCLC and demonstrated a higher proportion of CD36+CD8+ T cells in NSCLC tissues than that in non-tumor tissues, which was positively correlated with TNM stage." (PMID 37085798, 2023). "CD36 promotes FAO, angiogenesis, and tumor chemoradiotherapy resistance by regulating the Src/PI3K/Akt signaling pathway." (PMID 37064872, 2023). "The immunosuppressive effect of MDSC is inhibited by the STAT5 or STAT3 signaling reduction, or the genetic removal of the fatty acid translocase CD36, resulting in improved CD8+ T cell performance and slower tumor development." (PMID 37735675, 2023). "Suppressing CD36 in CD8+ T cells reduces intracellular lipid accumulation and reinstates their anti-tumor activity, while targeting CD36 in Treg cells mitigates their immunosuppressive effects." (PMID 37700339, 2023). "Inhibitors targeting to CD36 can restore the anti-tumor immune response in HCC and synergistically enhance the anti-tumor effect of anti-PD-1 therapy." (PMID 37700339, 2023). "Accumulation of CD36+CD8+ T cells in tumor tissues was correlated with more advanced stage (p < 0.001), larger tumor size (p < 0.01), and lymph node metastasis (p < 0.0001) in NSCLC." (PMID 37085798, 2023). "Consistent with the in vitro data, the miR-3180 inhibitor increased triglyceride and cholesterol levels in tumor tissues, while SCD1 or CD36 knockdown inhibited this effect." (PMID 37041584, 2023). "In primary lesions, the GLUT1 IHC score was positively correlated with GLS (R=0.51, p=0.01), and CD36 was negatively correlated with GLS (R=-0.43, p=0.04), which represented the canonical characteristics of tumor cell metabolism in primary lesions." (PMID 37207149, 2023). "For lipid metabolism, acidic conditions mediate the transport of FA by CD36 and promote the storage of PUFA in LDs, thereby increasing lipid accumulation in tumor cells." (PMID 37064872, 2023). "Furthermore, CD36 attenuation may be targeted to reduce tumour migration." (PMID 36816957, 2023). "We further confirmed that CD36 was mainly expressed in myoepithelial tumour cells in PA tissue by using Pan-Keratin (PCK), ACTA2 and CD36 multiple immunostainings." (PMID 37679344, 2023). "The mouse model demonstrated that miR-3180 inhibits HCC tumor growth and metastasis by inhibiting SCD1- and CD36-mediated de novo fatty acid synthesis and uptake." (PMID 37041584, 2023). "In several tumors, an increased expression of CD36 has been found, which seems to promote the EMT process and thus a more aggressive tumor phenotype." (PMID 37639069, 2023). "Our investigation indicates that miR-3180 is a critical regulator involved in de novo fatty acid synthesis and uptake, which inhibits HCC tumor growth and metastasis by suppressing SCD1 and CD36." (PMID 37041584, 2023). "We presented here that Rac1 activity but not RhoA or Cdc42 was increased significantly by PA treatment through CD36-Src-Akt signaling pathway, suggesting that Rac1 participated in triggering actin-remodeling and promoting LUAD tumor metastasis." (PMID 37612265, 2023). "Targeting CD36 in Treg cells can inhibit the polarization of M2-like macrophages, and may also supplement the blocking effect of PD-1 in treatment to offset the failure of tumor-infiltrating T cells, and reprogram TME, which may become a potential therapeutic target for clinical intervention in GC." (PMID 35444235, 2022). "In support of this, inhibiting CD36 reduces lipid uptake by CD8+ cells, increases their survival and allows them to better suppress tumor growth." (PMID 36038892, 2022). "The high expression of CD36, THBS1, and PDK4 in cancer is related to poor prognosis and promotes tumor progression." (PMID 36147333, 2022).